MCL1 (MCL1 apoptosis regulator, BCL2 family member)
Diseases named in the same sentence as MCL1 in open-access papers (continued):
Sharing a sentence is not in itself a finding about the gene and the disease.
colon carcinoma (69 papers, 2010 to 2025). "It was shown for human colon cancer that G2/M cell cycle arrest after Mcl-1 knockdown was caused by decreasing cyclin and CDKs (cyclin-dependent kinases) and increasing CDKI (cyclin-dependent kinase inhibitor) expression." (PMID 40892149, 2025). "Apigenin also inhibits the anti-apoptotic proteins Mcl-1 and Bcl-xL, causing colon cancer cells to die by blocking the phosphorylation of Signal transducer and activator of transcription 3 and therefore inducing apoptosis." (PMID 36144783, 2022). "Our results demonstrated that the cancer cell progression induced by M2 macrophages was mechanistically linked to FBW7-mediated MCL-1 stabilization in colon cancer cells." (PMID 32444799, 2020). "There were strong associations observed between the expression of Mcl-1 and that of Bcl-xL in both the lung and colon cancer samples." (PMID 23171055, 2012). "Myc has been shown to sensitize colon cancer cells to TRAIL induced apoptosis through repression of MCL1 and cIAP2 in bax deficient HCT116 cells." (PMID 20661477, 2010). "This seemed particularly relevant as resistance to the HDAC inhibitor vorinostat had been reported to depend on the phosphorylation level of Mcl‐1 in colon cancer models." (PMID 40483575, 2025). "These DMP micelles were stable and were capable of unifying and transmitting Bcl-xl siRNA and Mcl1 siRNA to colon cancer cells." (PMID 39339195, 2024). "Molecular docking analysis revealed that the DY-8 peptide exhibited binding affinity with Bcl-2, Bcl-xL, and Mcl-1, suggesting potential utility in combating colon cancer as functional food ingredients." (PMID 38870120, 2024). "This is consistent with previously published results for colon carcinoma cell lines showing that S63845 by binding to MCL-1 inhibits its activity but also increases MCL-1 protein half-life." (PMID 37835493, 2023). "The upregulation of the phosphorylation of Tyr705 in STAT3 is frequently detected in human colon cancers and can induce upregulation of anti-apoptotic protein such as Bcl-2, Bcl-xL, and Mcl1 expressions to prevent apoptosis of tumor cells in multiple tumors." (PMID 34900688, 2021). "Inhibition of STAT3 phosphorylation, resulting in downregulation of antiapoptotic proteins Mcl-1 and Bcl-xL and induces programmed cell death in colon cancer cells." (PMID 34539403, 2021). "For example, Apigenin induced apoptosis by simultaneously suppressing Bcl-xl and Mcl-1 in colon cancer." (PMID 34804180, 2021). "Inhibition of FBW7 expression with either siRNA in HEK293T cells, or genetic knockout via CRISPR/Cas9 in HCT116 colon cancer cells, completely rescued MCL1 levels in TRIP12-silenced and TRIP12-knockout cells, respectively." (PMID 33824312, 2021). "Data from colon cancer cell lines and a mouse xenograft model consistently showed that the AKT and ERK pathways were associated with FBW7-related MCL-1 degradation in M1 or M2 cocultured colon cancer cells." (PMID 32444799, 2020). "Western blotting results also indicated that FBW7 was involved in MCL-1 stabilization in colon cancer cells and mouse subcutaneous tumors that were cocultured with macrophages." (PMID 32444799, 2020). "In this study, cationic self-assembled DOTAP and MPEG-PCL hybrid micelles were prepared to deliver Bcl-xl siRNA and Mcl1 siRNA for treating C26 colon cancer." (PMID 31165329, 2019). "A recent study indicated that regorafenib induced colon cancer cell apoptosis via GSK-3β/Mcl-1 axis." (PMID 31168297, 2019).
colon carcinoma (continued). "We used Bcl-xl siRNA and Mcl1 siRNA as a therapeutic target, searching their antitumor effect for treating colon cancer in vitro and in vivo." (PMID 31165329, 2019). "Western blot analysis showed that BCLXL and MCL1 protein expression levels were similar between the parental and 5-FU-resistant cells in the three colon cancer cell lines." (PMID 31638265, 2019). "In colon cancer cells, extended exposure to lapatinib resulted in increased expression of MCL-1, decreased BAX expression, and inactivation of BAK." (PMID 30305055, 2018). "Studies have shown that MCL1 is a novel target of CUGBP2 wherein CUGBP2 binds to the MCL1 3′ UTR and increases MCL1 mRNA stability in colon cancers." (PMID 29361709, 2018). "Knockout of the rat Rac1 gene exon-3b or knockdown of endogenous Rac1b in HT29 human colon cancer cells downregulated only the AKT2/MCL1 pathway." (PMID 26918455, 2016). "For each we used RKO colon cancer cells in which there is substantial functional overlap between Bcl-xL and Mcl-1: while inhibition of either in isolation has little impact, inhibiting both is sufficient to induce apoptosis in the absence of cytotoxic insult." (PMID 27512141, 2016). "In previous studies, colon cancers showed a variable response to small-molecule-mediated Bcl-xL inhibition, and RNAi experiments identified Mcl-1 as a resistance factor." (PMID 27805565, 2016). "In summary, our work identifies EKR-mediated Mcl-1 stabilization via feedback activation of S6K1-IRS-2/PI3K as a novel resistance mechanism to mTOR inhibitors in BRAF600E colon cancer cells." (PMID 27351224, 2016). "Knockout of the rat Rac1 gene exon-3b or knockdown of endogenous Rac1b in human colon cancer HT29 cells downregulated only the AKT2/MCL1 pathway." (PMID 26918455, 2016). "Everolimus treatment disrupts the S6K1-IRS-2/PI3K negative feedback loop, leading to BRAF V600E-dependent activation of ERK and Mcl-1 stabilization in colon cancer cells, which in turn blocks the crosstalk from the death receptor to mitochondria." (PMID 27351224, 2016). "Immunoblotting showed that expression of the apoptosis-related Bcl-2-family protein Mcl-1 was decreased in miR-302s-transfected colon cancer cells, suggesting an involvement of the mitochondrial Bcl-2-family in miR-302s-induced apoptosis." (PMID 25970424, 2015). "A more recent report showed that miR-125a-5p plays an important role in inducing apoptosis through inhibiting the survival pathways mediated by aldehyde dehydrogenase 1a3 (aldh1a3) and myeloid leukemia–1 (mcl1) in colon cancer stem cells." (PMID 25504437, 2015). "In the first article, by using ChIP assay, the authors show that p65 subunit of NF-κB following TRAIL treatment binds to the Mcl-1 promoter, which suggested that TRAIL induced expression of Mcl-1 through activation of NF-κB in HCT-116 colon carcinoma cells." (PMID 24529193, 2014). "There were further relationships observed between Mcl-1 and Bcl-xL protein expression and tumor staging in colon cancer samples." (PMID 23171055, 2012). "To evaluate the correlation between Bcl-xL and Mcl-1 expression in lung and colon cancer, we analyzed human non-small cell lung adenocarcinoma and colon adenocarcinoma samples by immunohistochemistry using antibodies against these two proteins." (PMID 23171055, 2012). "In addition, miR-148a can directly target ROCK1/c-Met to inhibit Mcl-1 protein expression, thereby reducing angiogenesis and increasing apoptosis in colon cancer cells." (PMID 37259388, 2023). "We found that alisertib and danusertib, two small-molecule inhibitors of AURK, are inefficient inducers of apoptosis in HCT116 and DLD-1 colon cancer cells, the survival of which requires at least one of the two antiapoptotic Bcl-2 family proteins, Bcl-xL and Mcl-1." (PMID 36621626, 2023). "Therefore, MCL-1, as a central regulator of these features, was examined in colon cancer cells that were cocultured with macrophages." (PMID 32444799, 2020).
colon carcinoma (continued). "Furthermore, degradation of Mcl-1 in colon cancer is required for targeted therapeutics induced tumor suppression." (PMID 32276600, 2020). "The mechanisms by which miR-125 regulate CRC forms a complex network, miR-125 could negatively modulate BCL2, BCL2L12, and Mcl-1, and down-regulated miR-125 promoted colon cancer cell proliferation and inhibited apoptosis." (PMID 31782506, 2019). "Since HSP70/BAG complexes protect cancer cells from apoptosis through stabilization of anti-apoptotic Bcl-2 family member proteins, the downregulation of HSP70/BAG3 significantly reduces the levels of BCL-2, BCL-XL, and myeloid cell leukemia 1 (MCL-1) proteins in human HCT-116 colon cancer cells." (PMID 31878360, 2019). "We stained paraffin sections from colon cancer biopsies of three individuals with antibodies against Aconitase 2 as a reporter of mitochondrial mass and, simultaneously, against one of the proteins Bax, Bcl-2, Bid, Mcl-1, Smac, XIAP, Casp8 and Bar." (PMID 29374163, 2018). "Furthermore, knockdown of MCL-1 enhanced the effect of lapatinib whilst knockdown of BAK resulted in the inhibition of apoptosis in the colon cancer cells." (PMID 30305055, 2018). "However, overexpression of CUGBP2 in colon cancer cells reduces MCL1 protein levels possibly due to its inhibitory effect on translation." (PMID 29361709, 2018). "However, the expression of Bcl2, Mcl-1, Survivin and Bclxl decreased significantly in all three colon cancer cell lines when treated with the combination of oxaliplatin and dovitinib." (PMID 24495750, 2014). "We have previously shown that sorafenib downregulates Mcl-1 levels in colon cancer." (PMID 24086526, 2013). "Similar findings were reported for Mcl-1 and cIAP2 in colon cancer as well." (PMID 23029106, 2012). "Our data showed that proteasome inhibitors induced not only Bik but also Mcl-1 accumulation in several cancer cell lines, particularly human colon cancer cell lines, and that this accumulation was mainly due to the stabilization of the Mcl-1 protein by proteasome inhibitors." (PMID 22078414, 2011). "Moreover, miR-101 regulated the expression of Mcl-1 in liver cancer cells and regulated cyclooxygenase-2 in colon cancer cells." (PMID 21205300, 2011). "However, our hypothesis was based on analyzing near-diploid, karyotypically stable colon cancer cell lines where the overlapping functions of Mcl-1 and Bcl-xL contribute to pro-survival activity." (PMID 40466638, 2025). "In addition, long-term treatment with 5FU leads to increased expression of thymidylate synthase (TS), Bcl-1, Bcl-XL and Mcl-1 as well as increased activity of deoxyuridine triphosphatase and methylation of MLH1, which are associated with 5FU resistant colon cancers (reviewed in 68)." (PMID 35910798, 2022). "Also, Mcl-1 degradation is required for targeted therapeutics to eradicate colon cancer cells." (PMID 32081857, 2020). "NF-κB has been shown to play a role in TRAIL-induced Mcl-1 expression in HCT-116 colon cancer cells and the interaction of p65 subunit with Naa10p reportedly regulates Mcl-1 expression, However, whether NF-κB is involved in Mcl-1 expression in human ESCC cells remains to be clarified." (PMID 24529193, 2014). "In this study, we affirmed that miR-148a indirectly inhibited the expression of HIF-1α and Mcl-1 by directly binding to ROCK1 and c-Met, thereby enhancing apoptosis of colon cancer cells and decreasing angiogenesis in tissues containing such cells." (PMID 35997665, 2022). "In this current study, we supposed that miR-148a directly targets ROCK1 and c-Met to decrease angiogenesis and increase the apoptosis of colon cancer cells by inhibiting the secretion of VEGF and Mcl-1 through downregulation of HIF-1α under hypoxia." (PMID 35997665, 2022). "We found that colon cancer cells—and in particular Caco-2 and HCT116 cells—express high levels of Mcl-1 that were dramatically downregulated by MPE exposure for 48 h." (PMID 34299603, 2021).
colon carcinoma (continued). "Programmed death in colon cancer cells can be induced by inhibition of STAT3 phosphorylation, thereby downregulating the antiapoptotic proteins Bcl-XL and Mcl-1." (PMID 34539403, 2021). "Utilizing HCT116 colon carcinoma and stem‐like GBM cells, we found that inhibition of Bcl‐xL was most relevant to enhance the apoptotic effects of LXR agonists, followed by Mcl‐1 and Bcl‐2 inhibition (and EV3A and B)." (PMID 31468706, 2019). "To test this, we turned to DLD-1 cells, another colon cancer cell line which, compared with RKO, has a relatively lower level of Mcl-1." (PMID 27512141, 2016). "In the current study, we identified Mcl-1 upregulation and BRAF600E as resistance mechanisms of mTOR inhibitors in colon cancer cells and in xenografts." (PMID 27351224, 2016). "The induction of apoptosis in colon cancer cells by 3BP was confirmed by the downregulation of XIAP, cIAP1, cIAP2, Mcl-1, and Bcl-2 protein levels and the upregulation of Bax protein level." (PMID 26054380, 2015). "We performed the same analyses in a series of 79 colon tumor samples and observed a moderate correlation between the expression of USP9X and Mcl-1 (r=0.345, P<0.001)." (PMID 23171055, 2012). "E.g., Mcl-1 upregulation in response to S63845 was seen in tumor cell lines of breast and colon cancer, rhabdomyosarcoma, and T-ALL, and may be understood as a kind of cellular counter-regulation, based on induced Mcl-1 stability." (PMID 36902392, 2023). "Finally, our research demonstrated that miR-148a downregulated HIF-1α/VEGF and Mcl-1 by directly targeting ROCK1/c-Met to decrease angiogenesis and increase the apoptosis of colon cancer cells." (PMID 35997665, 2022). "Furthermore, inhibiting the Mcl-1, ERK and AKT, and prosurvival regulators with apigenin enhances ABT-263-induced antitumor activity in colon cancer cells." (PMID 36144783, 2022). "In addition to Bid, antiapoptotic Bcl-2, Bcl-xL, Mcl-1 and XIAP proteins have been shown to be cleaved by cathepsins during induction of apoptosis of various malignant cells, including human colon carcinoma cells." (PMID 26461472, 2017). "We recently reported that mTOR inhibitors induce apoptosis via ER stress and the extrinsic pathway upon acute inhibition of the eIF4F complex in colon cancer cells and xenografts, while mutant BRAF600E leads to therapeutic resistance via ERK-mediated Mcl-1 stabilization." (PMID 28030835, 2017). "Knockdown of AMPK or MCL-1 enhances aspirin-induced apoptosis in HCC and colon cancer cells." (PMID 26918349, 2016). "Indeed, by using a potent and selective BCL-XL inhibitor, A-1155643, we have shown that BCL-XL inhibition is sufficient to kill colon cancer cell lines expressing high levels of BCL-XL and the MCL-1-neutralizing protein NOXA." (PMID 26134786, 2015). "Interestingly, miR-125a-5p was reported to be a direct regulator of the anti-apoptotic genes BCL2, BCL2L12, and Mcl-1 in colon cancer cells in a negative manner." (PMID 35846752, 2022). "Moreover, previous studies have found that miRNA-101 inhibits the cell proliferation and augmented apoptosis in gastric cancer, colon cancer and NSCLC by targeting zinc finger E-box binding homeobox 1 (ZEB1), cyclooxygenase-2 (Cox-2), enhancer of zeste homologue 2 (EZH2) and Mcl-1." (PMID 32212793, 2020). "In addition, a study in some colon cancer cells found that no change in MCL-1 expression after treatment of these cells with aspirin." (PMID 26918349, 2016). "Taken together, our results demonstrate that Everolimus treatment disrupts the S6K1-IRS-2/PI3K negative feedback in colon cancer cells and leads to BRAF600E-dependent activation of EKR and Mcl-1 stabilization." (PMID 27351224, 2016).
gastric cancer (66 papers, 2013 to 2026). A primary or metastatic malignant neoplasm involving the stomach. "Just to cite an example: one study found that IL-6 efficiently protects gastric cancer cells from apoptosis caused by hydrogen peroxide (H2O2) by increasing the production of Mcl-1 (an anti-apoptotic protein)." (PMID 37759738, 2023). "In this study, LH was proved to cause cell cycle arrest at S phase and induced apoptosis in gastric cancer by inhibiting MCL1, which is consistent with the previous reports that MCL1 is involved in cell cycle by improving the stability of CDK2 protein." (PMID 33126914, 2020). "In many cancers including gastric cancer, Mcl-1 is overexpressed and is associated with patient survival and tumor progression." (PMID 31351462, 2019). "Together, these results demonstrate that downregulation of Mcl-1 in Genipin-treated gastric cancer cells causes apoptosis." (PMID 31351462, 2019). "Interestingly, Kaplan‐Meier analysis found that higher MCL‐1 expression was significantly associated with shorter overall survival in patients with gastric cancer." (PMID 31497917, 2019). "Univariate and multivariate analyses further suggested that Mcl1 overexpression was an independent prognostic marker for gastric cancer." (PMID 40765835, 2025). "In the present study, we demonstrated that Mcl-1 overexpression protected not only skin cancer cells but also gastric cancer cells from IMQ-induced cytotoxicity." (PMID 39272918, 2024). "The overexpression of miR-512 can decrease the expression of Mcl-1, resulting in the apoptosis of gastric cancer cells." (PMID 38920983, 2024). "Elgendy and colleagues reported that PPA2 activated the downstream glycogen synthase kinase 3β (GSK3β), which led to the decline of pro-survival protein MCL-1 and mediated metformin-induced gastric cancer cell death." (PMID 37470692, 2023). "When AGS human gastric cancer cells were treated with quercetin, anti-apoptotic Bcl-2, Mcl-1, and Bcl-x protein expression were decreased, and pro-apoptotic proteins such as Bad, Bid, and Bax protein expression was increased." (PMID 35971151, 2022). "Suppression of MCL-1 produced a significant increase in apoptosis and up to 60% decrease in gastric cancer cell growth." (PMID 35221802, 2022). "In gastric cancer, MCL-1 expression has been correlated with poor prognosis and resistance to chemotherapy." (PMID 35221802, 2022). "Han’s study found that MYOSLID plays a key role in the incidence and progression of gastric cancer through the MYOSLID-miR-29c-3p-MCL-1 axis." (PMID 35237659, 2022). "It is found that HMGB1-mediated autophagy decreases vincristine-induced apoptosis in gastric cancer partly via upregulation of Mcl-1, a Bcl-2 family member." (PMID 34933679, 2021). "In this study, we showed that LH has an anti-tumorous effect by down-regulating MCL1 in gastric cancer." (PMID 33126914, 2020). "In view of the previous reports, we knew that MCL1 is highly expressed in gastric cancer, and the prognosis of patients with high expression of MCL1 is worse." (PMID 33126914, 2020). "Immunohistochemical (IHC) staining with MCL1 further supported the results that LH inhibited tumorigenicity in gastric cancer through down-regulating the expression of MCL1." (PMID 33126914, 2020). "As reported, MCL1 is highly expressed in gastric cancer, and the prognosis of patients with high expression of MCL1 is worse." (PMID 33126914, 2020). "The qRT-PCR assay showed that the transcriptional level of MCL1 in BCL2-drug-resistant gastric cancer cell lines was higher than that in normal gastric cancer cell lines." (PMID 33126914, 2020). "Genipin also downregulated the protein levels of Mcl-1 in the other gastric cancer cell lines MKN45 and SNU638." (PMID 31351462, 2019). "Taken together, these results implicate Genipin in the induction of apoptotic cell death via JAK2/Stat3-regulated Mcl-1 suppression, suggesting that Genipin can potentially be an effective therapy for treating gastric cancer." (PMID 31351462, 2019).